GOLGA3 (golgin A3)
Description:
Golgi auto-antigen; probably involved in maintaining Golgi structure.
Synonyms: GCP170; golgin-160; MEA-2
Tractability: Antibody: UniProt places it where antibodies can reach, with medium confidence. PROTAC: ubiquitination databases record sites on it; its protein half-life has been measured.
Gene: Protein-coding gene on chromosome 12 (132,768,902 to 132,829,143, reverse strand). Ensembl gene ENSG00000090615.
Subcellular location: Cytoplasm; Golgi apparatus, Golgi stack membrane
Subcellular location (Human Protein Atlas): Golgi apparatus; Nucleoplasm
Pathways (Reactome):
Signal Transduction: RND2 GTPase cycle
Gene Ontology:
Molecular function: cadherin binding; protein binding
Cellular component: cytosol; Golgi apparatus; Golgi membrane; membrane; cytoplasm; Golgi cisterna membrane
Genetic constraint (gnomAD): Loss-of-function variants: 68 observed, 146.53 expected, observed/expected ratio (o/e) 0.46, 90% interval 0.38 to 0.57. The upper end of that interval is the gene's LOEUF score, 0.57, which puts it in group 2 of 6, group 1 being the genes least tolerant of losing a copy. Missense variants: 1,785 observed, 1,819.1 expected, observed/expected ratio (o/e) 0.98, 90% interval 0.94 to 1.02. Synonymous variants: 785 observed, 785.9 expected, observed/expected ratio (o/e) 1, 90% interval 0.94 to 1.06.
Homologues: Orthologues: chimpanzee GOLGA3 (99% identical), macaque GOLGA3 (92% identical), pig GOLGA3 (83% identical), guinea pig GOLGA3 (82% identical), mouse Golga3 (81% identical), rat Golga3 (81% identical), dog GOLGA3 (81% identical), rabbit GOLGA3 (70% identical), tropical clawed frog golga3 (65% identical), zebrafish golga3 (59% identical), Drosophila melanogaster GCC185 (7% identical). Paralogues in human: NUMA1 (20% identical), GCC2 (16% identical), CEP164 (12% identical).
Diseases named in the same sentence as GOLGA3 in open-access papers:
GOLGA3 is named in the same sentence as 17 diseases in open-access papers, as found by Europe PMC text mining. Sharing a sentence is not in itself a finding about the gene and the disease. The quoted sentences say what the papers report.
schizophrenia (2 papers, 2007 to 2023). A major psychotic disorder characterized by abnormalities in the perception or expression of reality. "Among highly ranked genes lacking SFARI Gene scores and OMIM annotations, previous studies suggest association with NDDs and schizophrenia [OBSCN, PLEC, RYR2, ZSWIM8], cortical formation and thickness [LAMA5, GOLGA3), and neurodegenerative diseases (PKHD1, DNAH1]." (PMID 35596027, 2023).
dysplasia (1 paper, 2025). A usually neoplastic transformation of the cell, associated with altered architectural tissue patterns. "Interestingly, skeletal dysplasia has not been reported in existing studies of Golga3/Golgin-160 mutant mice, which seems incongruous with the similarities seen here between GMAP210 and Golgin-160 KO ECM defects." (PMID 40824304, 2025).
Infertility (1 paper, 2023). "Although infertility was observed in Golga3 KO male mice and even though GOLGA3S465L showed weakened Golgi localization with protein visible in cytoplasm, this abnormal localization of GOLGA3 did not adversely affect fertility or spermatogenesis in male C57BL/6 mice." (PMID 37090114, 2023).
male infertility (1 paper, 2023). The inability of the male to effect fertilization of an ovum after a specified period of unprotected intercourse. "At the same time, lower sperm concentrations and motility in the caudal epididymis were found to lead to male infertility in Golga3 KO mice." (PMID 37090114, 2023).
testis atrophy (1 paper, 2023). "As previously reported, the loss of germ cells and obvious vacuolation leads to testis atrophy in Golga3 KO mice." (PMID 37090114, 2023).
GOLGA3 also shares sentences with these, for which no sentence is quoted: bladder cancer (3 papers); prostate carcinoma (3); cervical cancer (2); colorectal cancer (2); esophageal cancer (2); esophageal squamous cell carcinoma (2); cancer (1); COVID-19 (1); gastric cancer (1); neurodegenerative disease (1); non-small cell lung carcinoma (1); tumor (1).